STARD3 (StAR related lipid transfer domain containing 3)
Diseases named in the same sentence as STARD3 in open-access papers (continued):
Sharing a sentence is not in itself a finding about the gene and the disease.
esophageal cancer (2 papers, 2017 to 2019). A primary or metastatic malignant neoplasm involving the esophagus. "Genes co-amplified with ERBB2 (GRB7, MIEN1, PGAP3, and STARD3) exhibited the highest amplification frequency in esophageal cancer, followed by stomach, breast, uterine, and bladder cancer." (PMID 29190909, 2017). "Of note, the late endosomal membrane protein STARD3 (also known as metastatic lymph node 64), with ~37% C-terminal homology to StAR, was initially cloned as a gene amplified in the breast, gastric, and esophageal cancers." (PMID 31060224, 2019).
invasive breast carcinoma (2 papers, 2021 to 2023). A carcinoma that infiltrates the breast parenchyma. "We analyzed by IHC STARD3 protein expression in 112 HER2-positive invasive breast cancers on the initial tumor biopsies." (PMID 36672312, 2023). "In Gluck’s dataset, STARD3 was significantly overexpressed in invasive breast carcinoma compared to normal breast tissues (P = 1.33E-4)." (PMID 34268252, 2021).
osteoporosis (2 papers, 2022). A condition of reduced bone mass, with decreased cortical thickness and a decrease in the number and size of the trabeculae of cancellous bone (but normal chemical composition), resulting in increased fracture incidence. "STARD3 N‐terminal like (STARD3NL) showed robust association with osteoporosis‐related traits." (PMID 35098646, 2022).
acute lymphoblastic leukemia (1 paper, 2024). Leukemia with an acute onset, characterized by the presence of lymphoblasts in the bone marrow and the peripheral blood. "To gain further insight into the exclusivity of the PPP1R1B::STARD3 fusion, we analyzed two RNA-seq data profiles (including GSE115525 and PRJNA589314) for B-cell acute lymphoblastic leukemia (B-ALL) samples." (PMID 38835078, 2024).
age-related macular degeneration (1 paper, 2021). Age-related loss of vision in the central portion of the retina (macula), secondary to retinal degeneration. "However, the age-related decrease in the relationship between lutein and StARD3 could lead towards the primary cause of blindness in currently aging societies, which is age-related macular degeneration (AMD)." (PMID 34681572, 2021).
Alzheimer disease (1 paper, 2016). A progressive, neurodegenerative disease characterized by loss of function and death of nerve cells in several areas of the brain leading to loss of cognitive function such as memory and language. "Furthermore, the relationship between total lutein and StARD3 remained statistically significant after adjusting for presence of Alzheimer’s disease (r = 0.64, P < 0.05), and also after adjusting for covariates age, sex, and presence of Alzheimer’s disease (r = 0.60, P < 0.05)." (PMID 27205891, 2016).
atherosclerosis (1 paper, 2023). A disease characterized by the build-up of fatty material and calcium deposition in the arterial wall resulting in partial or complete occlusion of the arterial lumen. "Finally, STARD3 has a potential interest in other non-tumoral pathologies, such as hepatitis C and atherosclerosis." (PMID 36672312, 2023).
cervical adenocarcinoma (1 paper, 2025). An adenocarcinoma arising from the cervical epithelium. "Similarly, in cervical adenocarcinomas, the integration of HPV DNA into hotspots such as STARD3 and ERBB2 was correlated with increased protein expression pf STARD3 and ERBB2, respectively." (PMID 39858090, 2025).
colorectal cancer (1 paper, 2024). A primary or metastatic malignant neoplasm that affects the colon or rectum. "This study aims to identify STARD3 is involved in colorectal cancer and to demonstrate its part in treatment sensitivity measured in tumor derived organoids." (PMID 39309690, 2024).
coronary artery disease (1 paper, 2022). "It is important to note that the interactions between F2 rs3136441, LPA rs55730499, STARD3 rs881844, SCARB1 rs838880, and COBLL1 rs12328675 showed a strong contribution to the risk of coronary artery disease." (PMID 35203469, 2022).
dilated cardiomyopathy (1 paper, 2022). Cardiomyopathy which is characterized by dilation and contractile dysfunction of the left and right ventricles. "In addition to the known missense variant (rs2234962) in the BAG3 locus for dilated cardiomyopathy, we identify deleterious or damaging protein-coding variants in genes SYNPO2L, ERBB2, and STARD3 in strong LD with sentinel SNPs (LD R2 > 0.8)." (PMID 36517512, 2022).
ductal breast carcinoma in situ (1 paper, 2021). A carcinoma entirely confined to the mammary ducts. "Additionally, the expression of STARD3 was significantly higher (P = 0.011) in ductal breast carcinoma in situ than in normal breast carcinoma according to Curtis breast statistics." (PMID 34268252, 2021).
glioma (1 paper, 2015). A benign or malignant brain and spinal cord tumor that arises from glial cells (astrocytes, oligodendrocytes, ependymal cells). "Several genes including e.g. F5, LAMA1, ERBB2 or STARD3 seems to be in proximity to genes of the EGF/EGFR signaling cascade, which is known to be important in glioma." (PMID 25537509, 2015).
Hepatic steatosis (1 paper, 2024). Steatosis is a term used to denote lipid accumulation within hepatocytes. "Based on the findings presented in this review, the current evidence supports lutein and STARD3 as promising nutraceutical and therapeutic targets, respectively, for treating hepatic steatosis." (PMID 38978979, 2024). "This review summarizes current knowledge on the role of lutein in lipophagy, the pathways it is involved in, its relationship with STARD3, and its potential as a pharmacological strategy to treat hepatic steatosis." (PMID 38978979, 2024). "The significance of its transporter, STARD3, is not well-documented, and we believe that further research into the role of STARD3 in the pathogenesis of hepatic steatosis is warranted." (PMID 38978979, 2024).
Hereditary breast cancer (1 paper, 2019). Breast carcinoma that has developed in relatives of patients with history of breast carcinoma. "Among the highest-scoring genes detected using the proposed method, it is suspected that STARD3, PGAP3, ORMDL3, PSMD3 and HAPLN3 are the biomarkers of the HER2 + subtype, thus indicating that FOXC1 can identify basal-like subtypes in hereditary breast cancer cohorts." (PMID 31296201, 2019).
invasive carcinoma (1 paper, 2023). A carcinoma that is not confined to the epithelium, and has spread to the surrounding stroma. "Because the presence of DCIS is frequent in invasive carcinoma, we looked for STARD3 expression in the in situ and invasive components of tumors from our series." (PMID 36672312, 2023). "Interestingly, like HER2, STARD3 overexpression is stable during the transition of in situ to invasive carcinomas." (PMID 36672312, 2023).
lipid metabolism disorders (1 paper, 2025). "Targeting lipid transport proteins such as StARD3 or VAPB may reduce neuroinflammation caused by lipid metabolism disorders." (PMID 41456957, 2025).
liver cancer (1 paper, 2021). An epithelial or non-epithelial malignant neoplasm that arises from the liver. "However, we found that STARD3 has the highest expression levels in BC tissues compared with other types of cancers, such as prostate and liver cancers." (PMID 34268252, 2021).
Niemann-Pick disease (1 paper, 2022). A group of inherited, severe metabolic disorders in which sphingomyelin accumulates in lysosomes in cells. "This is likely due to the existence of unique transporters that transfer cholesterol to other organelles, such as the lysosome-mitochondrial transporter STARD3, which is implicated in Niemann–Pick disease." (PMID 35884604, 2022).
ovarian serous cystadenocarcinoma (1 paper, 2023). A malignant serous cystic epithelial neoplasm arising from the ovary. "The top five interacting genes were selected for analysis, and the results showed that PGAP3, GRB7, STARD3, and PSMD3 had a significant positive correlations with STAT3 in TCGA cancers, such as ovarian serous cystadenocarcinoma (OV)." (PMID 36977736, 2023).
premature ovarian failure (1 paper, 2025). "In this paper, we found that FOXL2 RNAi would upregulate StARD3 expression, suggesting that FOXL2 can inhibit StARD3 expression, reduce progesterone synthesis, and prevent premature ovarian failure." (PMID 41007402, 2025).
cancer (22 papers, 2011 to 2025). A tumor composed of atypical neoplastic, often pleomorphic cells that invade other tissues. "On the other hand, FBXL20 has been linked to chemotherapy resistance in cancer, while the suppression of STARD3 expression induces cell death in BC, and its high expression is associated with poorer survival." (PMID 40136626, 2025). "An analysis of the COSMIC (Catalog of Somatic Mutations in Cancer) database reveals a number of STARD3 somatic mutations in several tumor types." (PMID 34572920, 2021). "However, in HER2-amplified cancer, where STARD3 is overexpressed to high levels, functional studies showed that STARD3 silencing is associated with reduced cell growth." (PMID 36672312, 2023). "These genes warrant further investigation to inform their potential as biomarkers, particularly considering the previous success in targeting and inhibiting STARD3 in other cancers." (PMID 40506516, 2025). "STARD3 expression was scored according to signal intensity, the number of positive cancer cells, and staining patterns." (PMID 36672312, 2023). "It appears that in contrast to other cells, STARD3 function cannot be rescued in HER2-positive cancer cells, indicating a specific role for STARD3 in these cells." (PMID 36672312, 2023). "All these studies are consistent and demonstrate that HER2-amplified cancer cells have a specific dependency towards STARD3 expression." (PMID 36672312, 2023). "In the 104 STARD3-positive tumors, the protein was overexpressed in almost all cancer cells, but in rare cases, heterogeneity was observed." (PMID 36672312, 2023). "STARD3 is present in the HER2 minimal region of amplification in cancers, and importantly, STARD3 functions in HER2+ cancer cells." (PMID 36672312, 2023). "The development of anti-STARD3-targeted therapies represents a promising strategy for cancer patients with elevated STARD3 expression." (PMID 34572920, 2021). "The distribution of STARD3 expression in different types of human cancers (n =33) in comparison to adjacent normal tissues was obtained from the GEPIA web-based RNA expression tool." (PMID 34268252, 2021). "To the best of our knowledge, for the first time, we summarize the role of STARD3 in cancer and computational strategies to propose possible binding sites of potential STARD3 inhibitors and challenges for the discovery of new inhibitors." (PMID 34572920, 2021). "We subsequently used the Oncomine database to compare the expression of STARD3 in cancer tissues with that in normal tissues." (PMID 34268252, 2021). "This review highlights the recent discoveries of the StAR-related lipid transfer protein domain 3 (STARD3) member of START proteins in cancer development and progression." (PMID 34572920, 2021). "The role of the STARD3 protein as a molecular target for the development of cancer therapies is also discussed." (PMID 34572920, 2021). "As STARD3 is a key protein in the cholesterol movement in cancer cells, it is of interest to identify inhibitors able to block its activity." (PMID 34572920, 2021). "Gene STARD3 was related to HER2 amplification in Luminal A versus HER2 (+) and HER2 (+) versus TNBC, and it linked to growth and survival of HER2-amplified cancer cells." (PMID 30866472, 2019). "Overexpression of PPP1R1B::STARD3 may increase cancer cell proliferation and tumorigenesis by activating the PI3K/AKT pathway." (PMID 38835078, 2024). "We also looked at the percentage of cancer cells positive for STARD3 in these samples." (PMID 36672312, 2023). "The reduction of STARD3 expression in HER2-positive cancer cell lines inhibit their growth." (PMID 37966613, 2023). "To date, five clinical studies evaluating STARD3 expression in cancer investigated prognosis." (PMID 36672312, 2023). "The reduction of STARD3 expression in HER2-positive cancer cell lines reduces their growth." (PMID 36672312, 2023).
cancer (continued). "Why HER2+ cancer cells are dependent on high STARD3 expression remains unclear, but given its role in cholesterol traffic, it is postulated that STARD3 acts on HER2 cancer cells biology by modulating cholesterol homeostasis." (PMID 36672312, 2023). "Although the molecular mechanism is still unclear, these data show that a high expression of STARD3 influences the accumulation of membrane cholesterol, which could contribute to cancer aggressiveness." (PMID 34572920, 2021). "Because STARD3 is highly expressed and contributes to cancer progression in BC, it may be considered a good biomarker and therapeutic target." (PMID 34268252, 2021). "Blocking cholesterol transportation through the inhibition of STARD3 activity could be an important strategy to treat cancer." (PMID 34572920, 2021). "STARD3 was overexpressed in BC more than the other types of cancer." (PMID 34268252, 2021). "It was demonstrated that several of these genes, including STARD3, could functionally contribute to the proliferation of cancer cells that present amplification of HER2." (PMID 34572920, 2021). "The highest expression of STARD3 was observed in BC compared with other types of human cancer." (PMID 34268252, 2021). "Here, we will focus on STARD3 and discuss its role in cancer development." (PMID 34572920, 2021). "In-depth molecular studies are needed to clarify which protein partners cooperate with STARD3 in each specific cancer type and to identify the molecular networks that could act to compensate STARD3 alterations for better therapeutic approaches." (PMID 34572920, 2021). "Some studies have suggested that STARD3 may be a promising target for cancer treatment." (PMID 37658368, 2023). "Thus, the coexpression pattern between ERBB2 and other genes, such as PGAP3, STARD3, and PNMT, may be a marker of cancer, and site mutations in the interaction anchors or dysregulation in interactions related to ERBB2 may be a new target for cancer studies." (PMID 36702236, 2023). "Altogether, considering different parameters of STARD3 expression in this series, we found a significant association between the absence of staining, the diffuse staining pattern, and the low number of positive cancer cells with “no PCR” group." (PMID 36672312, 2023). "Along these lines, STARD3 may increase the progression of HER2-positive cancer." (PMID 34572920, 2021). "In this way, STARD3 may enhance the progression of HER2-positive cancer." (PMID 32039198, 2019). "In order to precisely establish the relationship between DNA copy number and RNA expression levels for STARD3 and other genes from the HER2 amplicon in independent samples, we took advantage of the CCLE (Cancer Cell Line Encyclopedia) project." (PMID 36672312, 2023). "In addition, StARD3 has been linked to cholesterol overload in mitochondria in NPC1 deficiency, which supported roles for StARD3 in LE/Lys-Chol transport to mitochondria for steroidogenesis, mitochondrial well-being and energy production, all anti-apoptotic properties in cancer settings." (PMID 35806209, 2022). "As STARD3 is a cholesterol-specific START protein, the challenge is to switch off the abnormal function or expression of this protein in cancer cells." (PMID 34572920, 2021). "Overexpression of STARD3 in MCF7 cells resulted in dysregulation of cholesterol homeostasis and cancer progression by enhancing the HMG CoA reductase enzyme, which is responsible for cholesterol biosynthesis." (PMID 34268252, 2021). "Here we focus on the FFAT motif-containing proteins, STARD3 and STARD 11, and discuss their role in cancer." (PMID 32039198, 2019).
cancer (continued). "PPP1R1B::STARD3 may be considered a candidate for targeted therapies of the cholesterol metabolic and the PI3K/AKT signaling pathways involved in cancer development and progression." (PMID 38835078, 2024). "Consistent with this idea, silencing STARD3 by siRNAs in HeLa cells (an endometrium HER2-negative cancer cell line) has no impact on viability and cell growth." (PMID 36672312, 2023). "In this review, we report the latest discoveries on StAR-related lipid transfer protein domain 3 (STARD3), a member of the START family, which has a potential role in cancer, focusing on the structural and biochemical characteristics and mechanisms that regulate its activity." (PMID 34572920, 2021). "STARD3, a gene involved in steroidogenesis, is overexpressed in HER2-positive cancer cells and it seems worthy investigating whether it contributes to the lipid-rich phenotype described for HER2-positive tumors." (PMID 25098819, 2014). "Of note, StARD3-dependent cholesterol transfer in these cancer-related findings was not addressed." (PMID 35806209, 2022). "At the same time, STARD3 gene has no function in other cancer cells." (PMID 30866472, 2019). "In addition, studies have shown that PGAP3, GRB7, STARD3, and PSMD3 are significantly positively correlated with STAT3 in TCGA cancers; however, reports on these are lacking." (PMID 36977736, 2023).
tumor (13 papers, 2010 to 2025). "Of special importance is the discovery of two genes MDGA2 and STARD3 for which significant associations with many other tumour types have been previously found." (PMID 40506516, 2025). "For example, genes such as SYNE1 and STARD3 were classified in the UV radiation response pathway, suggesting their relation to the hallmark of “Genome Instability and Mutation”, one of the pillars of tumor development." (PMID 40136626, 2025). "Two intron variant SNPs of MGMT and STARD3 were identified that were significant survival predictors and may influence tumor biology." (PMID 34529172, 2022). "The data discussed herein suggest that STARD3 has a role on cholesterol transportation in tumor cells." (PMID 34572920, 2021). "Downregulation of PSORS1C1 was observed in the tumor tissues while STARD3 and NM23 gene expression increased, when compared with the adjacent normal tissues." (PMID 30662464, 2018). "STARD3 is necessary for cholesterol transfer and metabolism in tumor cells." (PMID 34268252, 2021). "Amplification and overexpression of other genes (such as GRB7, C17orf37 and STARD3) of the 17q12 region could contribute to tumor growth." (PMID 20932292, 2010). "Tumor heterogeneity regarding STARD3 overexpression in this series was rare (4%, n = 3/112 had a positive and a negative contingent), however a higher percentage of STARD3-positive tumor cells was significantly associated with pCR (p = 0.015)." (PMID 36672312, 2023).
neurodegenerative disease (1 paper, 2016). A disorder of the central nervous system characterized by gradual and progressive loss of neural tissue and neurologic function. "Given that StARD3 is also involved in cholesterol transportation, a process that is aberrant in neurodegenerative diseases, the potential protective function of lutein against these diseases remains to be explored." (PMID 27205891, 2016).
STARD3 also shares sentences with these, for which no sentence is quoted: Niemann-Pick type C disease (2 papers); acute myeloid leukemia (1); adenocarcinoma (1); atopic dermatitis (1); bladder cancer (1); cardiovascular disease (1); hepatitis C (1); hyperphosphatemia (1); infectious disease (1); Insulin resistance (1); intellectual disabilities (1); lysosomal storage disorder (1); pancreatic cancer (1); psoriasis (1); squamous carcinoma (1); viral infection (1).